CCR4 (C-C motif chemokine receptor 4)
Diseases named in the same sentence as CCR4 in open-access papers (continued):
Sharing a sentence is not in itself a finding about the gene and the disease.
prostate carcinoma (continued). "As expected, CCR4+ cells with a mononuclear lymphoid morphology were abundant in prostate cancer." (PMID 35131860, 2022). "Anti-Treg treatment, through CCR4 blockade, may be a promising therapeutic approach for advanced prostate cancer in dogs and some population of human patients." (PMID 35131860, 2022). "The aim of this study was to elucidate the role of CCR2 and CCR4 in prostate cancer progression." (PMID 28039457, 2017). "We first examined CCR2 and CCR4 mRNA expressions in human prostate cancer cells." (PMID 28039457, 2017). "Our results suggest that CCR2 and CCR4 play a critical role in prostate cancer progression." (PMID 28039457, 2017). "Because the phosphorylation of Akt (Ser473) was more strongly inhibited by the CCR4 antagonist than by the CCR2 antagonist, CCR4 may contribute more to prostate cancer cell migration than CCR2." (PMID 28039457, 2017). "The addition of CCL2 induced CCL22 and CCR4 production in prostate cancer cells." (PMID 28039457, 2017). "Interestingly, CCL2 treatment resulted in significant increases in CCR2 and CCR4 protein levels in prostate cancer cells and promoted recruitment of monocytes into the tumor microenvironment, where they differentiated into TAMs." (PMID 28039457, 2017). "CCR2 and CCR4 were expressed in human prostate cancer cell lines and prostate cancer tissues." (PMID 28039457, 2017). "Given the promising outcomes and favorable clinical responses of the anti-CCR4 treatment in the comparative canine trial, we examined whether the CCL17–CCR4 axis is associated with tumor-infiltrating Tregs and prognosis in patients with human prostate cancer." (PMID 35131860, 2022). "However, the role of CCR4 and the relationship between CCR2 and CCR4 in prostate cancer remains unknown." (PMID 28039457, 2017). "Blockade of CCR4 with the FDA-approved monoclonal antibody reduced tumoral Treg infiltration and improved survival time in dogs affected with bladder and prostate cancer." (PMID 39046599, 2024). "Double immunofluorescence analysis confirmed that Foxp3+ Tregs expressed CCR4 in the tumor microenvironment, indicating that CCL17–CCR4 axis possibly contributes to the infiltration of Tregs into canine prostate cancer tissues." (PMID 35131860, 2022). "SDF-1 in the microenvironment upregulates CCR4+MDSC infiltration in the lung, and accumulated MDSC in turns secrete more SDF-1 to form a positive feedback, which promotes the metastasis of CCR4+ prostate cancer cells." (PMID 34689842, 2021). "In vitro co-culture of monocyte-lineage cells with prostate cancer cells induce higher expression of CCL2, which promotes the expressions of CCR2 and CCR4 in prostate cancer cells." (PMID 28039457, 2017). "Taken together, these results suggest that the anti-CCR4 treatment depletes Tregs, leads to clinical responses, and improves survival without severe adverse events in dogs with advanced prostate cancer." (PMID 35131860, 2022). "Immunohistochemistry in serial sections of human tissues showed Foxp3+ and CCR4+ mononuclear lymphoid cells in prostate cancer but not in normal prostate." (PMID 35131860, 2022). "Notably, addition of CCL2 induced both CCL22 and CCR4 expression in prostate cancer cells; CCL22 subsequently promoted the migration and invasion of prostate cancer cells in an autocrine manner, via enhanced phosphorylation of Akt." (PMID 30871130, 2019). "However, to our knowledge, the expression and role of CCR4 in prostate cancer have not been reported so far, and little is known about the relationship between TAMs and the CCL2–CCR2 and CCL17/CCL22–CCR4 axes with regard to tumor migration and invasion in prostate cancer." (PMID 28039457, 2017). "Mogamulizumab reduced circulating CD4+Foxp3+ Tregs and CCR4+ Tregs but not CD8+ cytotoxic T cells and CD4+ helper T cells in dogs with prostate cancer." (PMID 35131860, 2022).
T-cell leukemia (14 papers, 2014 to 2025). A malignant disease of the T-lymphocytes in the bone marrow, thymus, and/or blood. "Fra-2 enhances CCR4 expression in adult T-cell leukemia, and HTLV-1 viral factor-generated GATA3 stimulates CCR4 expression in CD4+ T cells." (PMID 35222362, 2022). "In adult T-cell leukemia, aberrantly expressed FOSL2 has been demonstrated to induce CCR4 expression MDM2." (PMID 36092920, 2022). "Adult T-cell leukemia (ATL) cells express frequently CCR4 and can migrate in vitro to CCL17 and CCL22, ligands for CCR4." (PMID 24966464, 2014).
gastric cancer (13 papers, 2014 to 2025). A primary or metastatic malignant neoplasm involving the stomach. "It is possible that tumor-induced immunosuppression is influenced by the abnormal expression of CCR4 in human gastric cancer." (PMID 37259456, 2023). "Nevertheless, the suppression of gastric cancer tumors or leukemia in NOG-IL-15 Tg mice by in vitro-expanded NK cells in combination with anti-Her2 or anti-CCR4 antibody treatment, respectively suggests that these cells had potent cytotoxicity." (PMID 29222435, 2017). "In the omental milky spot micrometastases 12 hours, 7 days and 14 days after intraperitoneal injection, CCR4 was observed on or in the gastric cancer cells, constituent cells of the milky spot, mesothelial cells, blood cells and blood endothelial cells." (PMID 25245466, 2014). "Within sections of omental milky spot micrometastases, CCR4 was recognised on or in gastric cancer cells, constituent cells milky spots, blood cells and blood endothelial cells." (PMID 25245466, 2014). "CCR4 was expressed on or in the gastric cancer cells in the section of the omental milky spot micrometastases 12 hours, 7 days and 14 days after intraperitoneal injection." (PMID 25245466, 2014). "We therefore examined the expression of MDC/CCL22 and CCR4 in milky spot micrometastases, with the aim of establishing a new treatment method for preventing peritoneal metastasis by focusing on the chemotaxis of gastric cancer cells." (PMID 25245466, 2014). "Feasibly suppressing CCR4 expression could be a successful treatment for human stomach cancer." (PMID 37259456, 2023). "Although the exact mechanism of the altered proportions of CCR4+/CD3+ and central memory CD4+ cells in the gastric mucosa of patients with cancer is unknown, focusing on lymphocytes in the gastric mucosa might help improve our understanding of gastric cancer development after H. pylori eradication." (PMID 36569708, 2022).
pancreatic cancer (13 papers, 2016 to 2025). "In summary, the experimental results showed that loss of the CCR4 chemokine receptor or antagonization of CCR4 in mice conferred a significant survival advantage in mice suffering from pancreatic cancer." (PMID 37371612, 2023). "To examine the association between CCR4 and TAMs in pancreatic cancer, we analyzed the immune cell abundance in lysed tumors of CCR4−/− mice and wildtype mice via flow cytometry." (PMID 37371612, 2023). "It was recently shown that CCR4+ MDSCs (monocytic myeloid-derived suppressor cells) are linked to elevated EMT (epithelial–mesenchymal transition) in pancreatic cancer patients." (PMID 37371612, 2023). "Our analysis of CCR2 and CCR4 revealed their differential modulation upon macrophage polarization and pancreatic cancer cell coculture." (PMID 40282185, 2025). "Analogous to CCR4, the upregulated KCNN4 expression is associated with adverse prognosis in numerous malignancies, including papillary thyroid carcinoma, pancreatic cancer, and ccRCC." (PMID 41301871, 2025). "In this study, three groups of C57BL/6 mice were used to investigate the effects of inhibiting CCR4 on tumor growth in pancreatic cancer in a syngeneic tumor model." (PMID 37371612, 2023). "The results showed that genetic depletion or antagonization of CCR4 significantly decreased pancreatic cancer growth." (PMID 37371612, 2023). "Immunohistochemical sections of pancreatic tumors revealed that intratumoral macrophages were significantly decreased in CCR4−/− and CCR4-antagonized mice." (PMID 37371612, 2023). "CCL2 activates the cancer cell cytoskeleton and enhances the migratory properties of pancreatic cancer cells via CCR4." (PMID 37607005, 2023). "It was recently shown that the CCL17-eluting scaffold prevents tumor progress in pancreatic cancer by attracting CCR4+CD4+ T cells." (PMID 37371612, 2023). "This study identified the relevance of CCR4 on TAMs in pancreatic cancer and its therapeutic potential to target TAMs." (PMID 37371612, 2023). "Another therapeutic approach is the transduction of CCR4 to cytotoxic T cells, lymphocytes which accumulate in a tumor with a high expression of CCR4 ligands, for example, in pancreatic cancer, where they destroy cancer cells." (PMID 33182504, 2020). "In a phase I study of nivolumab plus mogamulizumab, a monoclonal antibody targeting CCR4, for patients with solid tumors, the partial response, and stable disease rates in 15 patients with pancreatic cancer were 7% and 33%, respectively." (PMID 31997007, 2020). "Further underlining the suitability of our in vitro model, both pancreatic cancer cell lines showed similar modulation of the critical macrophage polarization markers arginase, CD206, and iNOS, as well as chemokine receptors CCR2 and CCR4." (PMID 40282185, 2025). "Therefore, it is a potential immunological target to suppress TAM formation; in fact, CCR4 blockade improves prognosis in pancreatic cancer." (PMID 38542388, 2024). "Similarly, the results of our orthotropic pancreatic cancer model on CCR4−/− mice showed that the loss of CCR4 reduces tumor growth and prolongs survival in pancreatic cancer in vivo." (PMID 37371612, 2023). "CCR4 blockade may help prolong the relapse-free period after curative surgery in pancreatic cancer and improve prognosis." (PMID 37371612, 2023). "The second group received prophylactic CCR4 inhibition before pancreatic cancer injection." (PMID 37371612, 2023). "Specifically, histological sections of pancreatic carcinomas from CCR4−/− mice showed 0.14 ± 0.02% of F4/80+ area compared to sections of tumors from C57BL/6 wildtype mice, which showed 0.39 ± 0.06% macrophage staining in sections from pancreatic cancer-bearing wildtype C57BL/6 mice (p = 0.002)." (PMID 37371612, 2023). "It has been also confirmed that up-regulated expression of CCR4+CD8+ T cells could inhibit the liver metastasis of pancreatic tumor cells." (PMID 34737763, 2021).
pancreatic cancer (continued). "Our analyses revealed that the immune-related genes CCR4, CD19, TNFSF8, SH2D1A, ICOS, IGKV1D-39, and TNFRSF17 may be implicated in the immunophenotyping of pancreatic cancer." (PMID 34737763, 2021). "Based on our results, we suggest that antagonizing CCR4 could be beneficial as an adjuvant strategy in pancreatic cancer therapy to mitigate the immunomodulatory potential of the remaining cancer cells after curative surgery and prolong the relapse-free period." (PMID 37371612, 2023). "Since our work focused on chemokines in the context of pancreatic cancer cells driving macrophage polarization levels, we also investigated the relative surface marker expression of two chemokine receptors, CCR2 and CCR4." (PMID 40282185, 2025). "The CCL2/CCR4 axis plays a role as a chemoattractant of monocytes/macrophages in pancreatic ductal carcinoma (PDA) and in murine pancreatic cancer." (PMID 38542388, 2024). "This study examined the impact of genetic (CCR4−/−) and prophylactic or therapeutic pharmacological CCR4 blockade on TAM infiltration, pancreatic cancer growth, and animal survival in a murine orthotopic pancreatic cancer model." (PMID 37371612, 2023). "Our experiments revealed a benefit of the CCR4 antagonist AF399/420/18025 injected prophylactically and trending therapeutically in pancreatic-cancer-bearing wildtype mice." (PMID 37371612, 2023). "facilitating CD8 T cell–DC interactions via overexpression of the C-C chemokine receptor type 4 (CCR4) in CD8 T cells, enhance T cell antitumor responses against pancreatic tumor models." (PMID 32580431, 2020). "So in the hypoxia microenvironment of pancreatic cancer, blocking CCR2/CCR4 will likely have the potential to reduce the inflammation of pancreatic cancer tissue and fibrosis." (PMID 27271610, 2016). "Since we were also interested in the surface marker expression profiles of chemokine receptors CCR2 and CCR4, the expression of both was also measured using multicolor flow cytometry and found to associate moderately and strongly with pancreatic cancer ET ratios for CCR2 and CCR4, respectively." (PMID 40282185, 2025). "In a Pan02 pancreatic cancer mouse model, characterized by the secretion of the chemokines CCL17 and CCL22, the use of a CCR4 antagonist (CCR4-351) has shown significant effects in disrupting the CCR4-CCL17/CCL22 chemotactic axis, which effectively blocks the recruitment of Tregs to the TME." (PMID 38500876, 2024). "In this study, the cytokine‒cytokine receptor interaction pathway was the most enriched pathway between pancreatic cancer cells treated with and without glutamine, includingCCL5,CCR4,LTA,CXCR4,IL-6R, andIL-7R." (PMID 36942991, 2023). "In a phase I clinical study on solid tumors, the anti-CCR4 antibody mogamulizumab showed no reduction in the numbers of immunosuppressing Tregs in pancreatic cancer." (PMID 37371612, 2023). "The first group was a CCR4-knockout group that did not receive any pharmacological CCR4 inhibition before or after PDA6606 pancreatic cancer cells were implanted in the pancreas." (PMID 37371612, 2023). "CCR4 seems to be critically involved in TAM generation and tumor progression in pancreatic cancer." (PMID 37371612, 2023). "The C-C chemokine receptor type 4 (CCR4) is critical for immune cell recruitment into the TME, and in this paper we explore the effects of its genetic or immunotherapeutic blockade in pancreatic-cancer-bearing mice." (PMID 37371612, 2023). "The results revealed seven immune-related genes (CCR4, CD19, TNFSF8, SH2D1A, ICOS, IGKV1D-39, and TNFRSF17) could potentially influence the immunophenotyping of pancreatic cancer." (PMID 34737763, 2021). "Furthermore, the CCR4 antagonist AF399/420/18,025, which was also used in the present study, did not induce a reduction in T-cell numbers in the tumor tissue of the murine pancreatic cancer model." (PMID 37371612, 2023).
leukemia (12 papers, 2009 to 2025). A malignant (clonal) hematologic disorder, involving hematopoietic stem cells and characterized by the presence of primitive or atypical myeloid or lymphoid cells in the bone marrow and the blood. "Clinical trials of the humanized CCR4 antibody mogamulizumab were approved in Japan for the treatment of T-cell lymphomas, leukemia, and advanced solid tumors." (PMID 36555280, 2022). "In the treated and later infected groups, there was increased expression of TLR7 and CCR4, a chemokine receptor predominantly expressed by Th2 cells and related to inflammatory diseases and T cell neoplasms, such as leukemias and lymphomas." (PMID 36357780, 2022). "The chemokine receptor CCR4 has recently been found to be expressed on HTLV-1-infected leukemia cells in ATL patients." (PMID 21994794, 2011). "We further characterized the leukemia cells by analyzing their Foxp3 and CCR4 expression." (PMID 35906240, 2022). "Thus, the CD4+CD25+CCR4+ leukemia T cells with increased Treg function may also contribute to the clinically observed cellular immunodeficiency in ATL patients." (PMID 19654865, 2009). "It has been shown that Tregs strongly express CCR4, a chemokine receptor for CCL17 or CCL22, on their surface as compared to effector T cells in leukemia studies." (PMID 33816236, 2021). "In leukemia cells, we instead found a dominant association between CNOT3 (and the CCR4-NOT complex) and ribosomal proteins, tRNA synthetases, and translation elongation factors." (PMID 38491013, 2024). "Here the authors uncovered CNOT3, a subunit of the CCR4-NOT complex, as an essential modulator of translation in leukemia." (PMID 38491013, 2024). "Here, we demonstrated that the subunit CNOT3 of the CCR4-NOT complex is required for survival and growth of leukemia cells in vitro and in vivo." (PMID 38491013, 2024).
viral infection (12 papers, 2010 to 2025). "Notably, increases in the percentage of CD4+CCR4+ T cells are commonly found in inflammatory diseases, and the finding here is consistent with our previous results indicating that p12KO virus infection is associated with a higher inflammatory profile." (PMID 38668247, 2024). "Together with an increased expression of CCR4, especially after yellow fever vaccination, this would indicate that naïve rTreg that entered the peripheral blood were preparing for migration towards and interaction with activated antigen-presenting cells." (PMID 28658271, 2017). "Statistically higher percentages of CCR4+ CD4 TEM cells (61.94%) distinguished RSV-infected children from other viral infections (52.02%) and healthy controls (42.89%)." (PMID 25013801, 2014). "Interestingly, CCR4 and CCR5 expression was upregulated in CD8 T cells, both chemokine receptors have already been associated with other viral infections." (PMID 33784417, 2021). "However, regulation of CCR4 in virus infections is less understood." (PMID 32207684, 2020). "However, understanding of CCR4 functions in virus infections is limited." (PMID 32207684, 2020). "Virus infection also upregulated CXCR3 expression in CD4+ T-cells in MLN, as shown by the expansion of CXCR3+ (Student’s t-test, p = 0.002), CXCR3+CCR4+ (Student’s t-test, p = 0.007) and CXCR3+CCR5+CCR4+ CD4+ T-cell subsets (Student’s t-test, p = 0.001)." (PMID 34685494, 2021). "Down-regulation of IL15, NOS2A, CCR4 and up-regulation of IL17, CYP7A1, SELE, IL5, RPL3L genes in both patient categories indicative of response to p-H1N1-09 virus infection." (PMID 20957032, 2010). "These chemokines likely facilitate faster lymphocyte and monocyte-derived cell infiltration into the lungs, reflected by earlier upregulation of chemokine receptors CCR4, CCR5, and CXCR5, than seen with PJ73 and VR2332, helping counter viral infection and restore lung homeostasis." (PMID 40459260, 2025). "Currently, regulation of CCR4 and its deadenylase activity in viral infections is not well understood." (PMID 32207684, 2020). "Thus, it is possible that the host Ccr4-Not transcription complex may play some roles in viral replication during viral infection." (PMID 28536288, 2017). "Furthermore, we found that the differentially interacting protein CCR4-NOT complex 2 (CNOT2), identified in PEDV S1 with plasma membrane proteins of Vero cells, is involved in viral infection." (PMID 36140672, 2022).